KCNK1 (potassium two pore domain channel subfamily K member 1)
Diseases named in the same sentence as KCNK1 in open-access papers (continued):
Sharing a sentence is not in itself a finding about the gene and the disease.
Arrhythmia (2 papers, 2024). Any cardiac rhythm other than the normal sinus rhythm. "On the other hand, KCNK1 channels may be a molecular target for the treatment of cardiac arrhythmia and cancer." (PMID 38410243, 2024).
glioma (2 papers, 2021 to 2024). A benign or malignant brain and spinal cord tumor that arises from glial cells (astrocytes, oligodendrocytes, ependymal cells). "Moreover, multiple studies have demonstrated the association of KCNK1 with the development and prognosis of various cancers, including glioma, through its regulation of tumor cell proliferation and survival." (PMID 38584840, 2024).
pancreatic adenocarcinoma (2 papers, 2023 to 2024). "Aberrantly expressed KCNK1 was significantly associated with poor prognosis in a variety of cancers, such as BRCA, thyroid cancer, lung and pancreatic adenocarcinomas." (PMID 38689322, 2024).
thyroid cancer (2 papers, 2020 to 2024). "In thyroid cancer, KCNK1 can promote tumour malignancy through cell cycle, PI3K and MAPK signalling pathways." (PMID 38689322, 2024). "However, KCNK1, KCNK6, KCNK7, KCNK9, KCNK10, KCNK13 and KCNK16 mRNA expressions were not related to the prognosis of patients with thyroid cancer." (PMID 32742463, 2020).
astrocytomas (1 paper, 2020). "In particular, the expression of KCNK1 was decreased more in cancers of the overall CNS—such as astrocytomas (AC), GBMs, ODs, medulloblastomas, and melanomas—than in the normal tissue." (PMID 32906679, 2020).
Autoimmunity (1 paper, 2018). The occurrence of an immune reaction against the organism's own cells or tissues. "KCNK1 is a voltage-gated potassium channel upregulated by activated microglia and a mediator in amyloid-mediated microglial priming, additionally reactive oxygen species production that was shown to be related with autoimmunity." (PMID 30555656, 2018).
bladder cancer (1 paper, 2024). "This study aimed to explore the expression, molecular mechanism and its biological function of potassium two pore domain channel subfamily K member 1 (KCNK1) in bladder cancer (BC)." (PMID 38689322, 2024).
brain glioblastoma (1 paper, 2020). A WHO grade IV malignant astrocytic tumor that arises from the brain, usually the cerebral hemispheres. "In a related study, KCNK1, KCNK3, and KCNK10 were significantly downregulated in brain glioblastoma (GBM)." (PMID 32906679, 2020).
breast tumor (1 paper, 2022). "Among them, KCNK1/4/6/9/10/13/15 were upregulated in breast tumor samples compared to normal mammary tissues." (PMID 35656548, 2022).
hypophosphatemia (1 paper, 2025). Lower than normal levels of phosphates in the circulating blood. "Although TWIK-1 is not exclusively expressed in the PT, in mice, the knockout of TWIK-1/Kcnk1 results in hypophosphatemia owing to impaired phosphate transport in the PT, suggesting the role of TWIK-1 in the membrane trafficking of transport molecules in PTs and its potential link with SGLT2." (PMID 41458378, 2025).
lung carcinoma (1 paper, 2025). "Lung cancer studies included E3 (KCNK1), E8 (KCNK1, KCNN4), E12 (KCNH8, KCNMB2), E23 (KCNU1), E30 (KCNQ5-IT1), E35 (KCNK1), E43 (KCNK6), E49 (KCNN4), 2), E54 (KCNJ13), E63 (KCNK12), and E67 (KCNMB2)." (PMID 40867621, 2025).
neuropathic pain (1 paper, 2023). Chronic pain caused by damage to nerve fibers. "To further investigate whether spinal Kcnk1 is involved in the development of neuropathic pain, we used the lentivirus to overexpress Kcnk1 in the spinal cord of neuropathic pain mice." (PMID 37144575, 2023).
ovarian carcinoma (1 paper, 2022). A malignant neoplasm originating from the surface ovarian epithelium. "In our study, inorganic ion trans-membrane transports for calcium (TRPM3), sodium (SLC family) and potassium (KCNK1) were significantly up-regulated in the metastatic ovarian cancer samples compared to the primary ones, which were in accord with previous researches." (PMID 35915456, 2022).
type 2 diabetes (1 paper, 2019). "In our previous study using a genetic model of type 2 diabetes (the db/db mouse), we assessed potential effects on genes linked to cardiotoxicity genes (Kcnk1, Asah2, B4glant, MMP-3), and reported no adverse effects after ENOblock treatment." (PMID 30679508, 2019).
tumor (11 papers, 2019 to 2026). "Review of previous literature indicated that KCNK1 (Potassium Two Pore Domain Channel Subfamily K Member 1), a crucial member of the potassium channel family, is highly expressed in various cancers and significantly related to tumor prognosis and invasiveness." (PMID 40469299, 2025). "Previous research indicated that KCNK1 plays a very vital role in promoting tumour cell malignant transformation, especially in regulating cell cycle progression and cancer cell malignant proliferation and migration." (PMID 38689322, 2024). "The subcutaneous tumor model showed that the tumor volume of the nude mice in the KCNK1 overexpression group was larger compared with that of the control group, whereas it was smaller in the KCNK1 knockdown group." (PMID 38905316, 2024). "The progression-free analysis found that FAM90A1, ETS2, STAT6, MYT1L, ING2 and KCNK1 are related to tumour regrowth." (PMID 32015217, 2020). "The high expression of KCNK1 might be involved in the cell cycle, cellular metabolism, and tumour microenvironment through the regulation of potassium channels, and ultimately contributed to the deterioration of BC." (PMID 38689322, 2024). "Finally, we assessed the correlation of KCNK1 expression with the tumour microenvironment (TME) and clinical significance." (PMID 38689322, 2024). "Moreover, a total of 7 KCNKs were found to be closely related to the tumor stage, which were KCNK1, KCNK2, KCNK5, KCNK6, KCNK7, KCNK19, and KCNK15." (PMID 32742463, 2020). "We found the KCNK1 gene upregulated in regrowth tumours, which may indicate a more active metabolism status." (PMID 32015217, 2020). "And the expression levels of KCNK1/2/4/5/6/7/15 were correlated with the tumor stage." (PMID 32742463, 2020). "Therefore, KCNK1 might reduce the potential for tumour immune escape and enhance immune response (anti-CTLA-4 and anti-PD-1 combination therapy) by modulating elevated potassium ions." (PMID 38689322, 2024). "The gene KCNK1 is identified as a pivotal oncogene in LUAD, exerting a substantial influence on tumor progression and resistance to cisplatin." (PMID 40469299, 2025). "In this study, we have identified KCNK1 as a potential oncogenic biomarker for LUAD, highlighting its significant role in tumor progression and chemotherapy resistance." (PMID 40469299, 2025). "Meanwhile, the high KCNK1 expression group had lower TIDE scores, suggesting a low tumour immune escape potential and a better outcome of immunotherapy for BC patients (p = 5.7e-7)." (PMID 38689322, 2024). "Meanwhile, elevated KCNK1 expression resulted in lower stromal scores, immune scores, and ESTIMATE scores and higher tumour purity in TME." (PMID 38689322, 2024). "Together, these findings confirm that KCNK1, PCDH1, and SDR16C5 are aberrantly upregulated in PDAC and exhibit distinct yet complementary patterns of cellular distribution, implicating them as potential contributors to tumor progression." (PMID 41602375, 2026). "Additionally, genes such as KCNK1, SHMT2, and PYCR1, which influence tumor metastasis and invasion through histone lactylation, may also serve as biomarkers to help track tumor progression." (PMID 40057816, 2025). "Therefore, we speculated that high KCNK1 expression might increase BC TME potassium ions, thereby reducing the level of multiple immune cell infiltration and increasing tumour purity." (PMID 38689322, 2024). "We did not observe differential expression of KCNK1, KCNK2, or KCNK5 for different tumor grades." (PMID 31581133, 2019).
cancer (9 papers, 2013 to 2025). A tumor composed of atypical neoplastic, often pleomorphic cells that invade other tissues. "Additionally, aberrant expression of KCNK1 is associated with the malignancy of various cancers." (PMID 40469299, 2025). "MTT and colony formation experiments showed that the proliferation ability of cancer cells overexpressing KCNK1 was significantly enhanced." (PMID 38905316, 2024). "Considering that KCNK1 mRNA expression was significantly different in cancer and control samples, we plotted the ROC of each dataset to assess the distinguishing ability of KCNK1 mRNA." (PMID 38689322, 2024). "Therefore, we suggested that KCNK1 could promote the abnormal proliferation of cancer cells by activating potassium ion channel activity." (PMID 38689322, 2024). "Therefore, KCNK1 might mediate the abnormal cell cycle and metabolism of BC epithelial cells by controlling membrane ion channels, which ultimately promoted the proliferation of cancer cells." (PMID 38689322, 2024). "The data show that mRNA expression of KCNK1, KCNK7, and KCNK9 is upregulated in cancer tissues while KCNK2, KCNK3, KCNK5, KCNK10, KCNK13, KCNK15, and KCNK17 levels are decreased compared to controls." (PMID 31581133, 2019). "Despite the involvement of KCNK1 in various cancers, as documented in previous studies, its role in LUAD has not been reported." (PMID 40469299, 2025). "Therefore, membrane hyperpolarization due to the up-regulation of KCNK1/KCNK2 channel expression facilitates Ca2+ influx through ROC and SOC channels in IPAH-PASMCs, similar to that in non-excitable cells, such as epithelial, endothelial, immune, and cancer cells." (PMID 38410243, 2024).
KCNK1 also shares sentences with these, for which no sentence is quoted: atrial fibrillation (3 papers); Brugada syndrome (2); depression (2); Hypokalemia (2); pancreatic cancer (2); Alzheimer disease (1); amyotrophic lateral sclerosis (1); arrhythmogenic right ventricular cardiomyopathy (1); autism (1); Birk-Barel syndrome (1); Brain Diseases (1); cardiac arrhythmia (1); channelopathy (1); diabetes (1); dilated cardiomyopathy (1); epilepsy (1); epileptic seizures (1); glioblastoma (1); gynecological cancers (1); Hyperkalemia (1); idiopathic ventricular fibrillation (1); Intellectual disability (1); ischaemic cardiomyopathy (1); lymph node metastasis (1); mastitis (1); medulloblastoma (1); melanoma (1); mitral valve disease (1); papillary thyroid carcinoma (1); psychosis (1).
A further 2 diseases each share a sentence with KCNK1 in 1 paper.